TNF (tumor necrosis factor)
Diseases named in the same sentence as TNF in open-access papers (continued):
Sharing a sentence is not in itself a finding about the gene and the disease.
Insulin resistance (continued). "The pathogenic link between PsA and T2DM is not yet fully understood, but inflammatory cytokines, particularly TNF and IL-17, are known to impair insulin signaling and promote insulin resistance." (PMID 41266905, 2025). "IGF-1 was inversely associated with age, glycemic markers (fasting glucose, HbA1c), insulin resistance (HOMA-IR), TNF-α, and atherogenic lipids, while higher levels were linked to better insulin sensitivity." (PMID 41393761, 2025). "Adipokines are proinflammatory, such as TNF-α, IL-6, and resistin, which participate in inflammation and activation of other inflammatory pathways that lead to insulin resistance and metabolic diseases." (PMID 40013194, 2025). "VAT is metabolically active and contributes to systemic inflammation and insulin resistance by secreting increased amounts of pro-inflammatory adipokines, including tumor necrosis factor alpha (TNF-α) and interleukin-6 (IL-6)." (PMID 40013194, 2025). "Insulin resistance is connected to increased TNF-α expression, and IL-6 plays a key role in lipid buildup in the myocardium." (PMID 39791169, 2025). "IFN-γ also promotes M1 macrophage polarization and enhances the expression of TNF-α and IL-6, thereby exacerbating systemic inflammation and insulin resistance." (PMID 40869401, 2025). "MetS originates from energy imbalance, genetic/epigenetic, and lifestyle factors, mediated through free fatty acid-induced insulin resistance, IL-6/TNF-α-mediated inflammation, and fetuin-A-driven mitochondrial reactive oxygen species dysregulation." (PMID 40703156, 2025). "The DKD-related genes were found to be involved in several enriched pathways, including TNF signaling, growth hormone (GH) synthesis and action, insulin resistance (IR), and other signaling cascades." (PMID 41318413, 2025). "The observed stress hyperglycemia in Cluster 1 suggests enhanced gluconeogenesis and glycogenolysis, potentially driven by insulin resistance and counter-regulatory hormones such as catecholamines, cortisol, and pro-inflammatory cytokines (e.g., IL-6, TNF-α)." (PMID 40745510, 2025). "Secretions of tumor necrosis factor α (TNF-α) activated macrophage-induced insulin resistance in skeletal muscle in a dose-dependent manner." (PMID 40894926, 2025). "M1 MΦs secrete pro-inflammatory cytokines, such as tumor necrosis factor-alpha (TNF-α), interleukin-6 (IL-6), and interleukin-1 beta (IL-1β), which impair insulin signaling in adipocytes and contribute to insulin resistance." (PMID 41602577, 2025). "High-fat diets (HFDs) exacerbate this process by activating the Jun N-terminal kinases (JNK), TNF-α, and NF-κB signaling pathways, thereby amplifying inflammation and insulin resistance." (PMID 40564033, 2025). "Inflammatory mediators like TNF-α and IL-1β can impede insulin signaling pathways, intensifying insulin resistance and ultimately contributing to the advancement of T2DM and the onset of associated complications." (PMID 40519559, 2025). "Excess visceral fat secretes proinflammatory cytokines (TNF-α, IL-6) and adipokines (leptin), which promote oxidative stress and insulin resistance." (PMID 40702394, 2025). "A moderate positive correlation was observed between insulin resistance and TNF-α (r=0.6308, P=0.0088)." (PMID 40862455, 2025). "Inflammatory pathways and oxidative stress—driven by NADPH oxidase activation and proinflammatory cytokines such as TNF‐α and IL‐6—also contribute to insulin resistance by inducing serine phosphorylation of IRS‐1 and impairing insulin receptor activity." (PMID 41143273, 2025). "ST reduced BW, epididymal and visceral fat depots, triglycerides, total cholesterol, glucose, leptin, and tumor necrosis factor (TNF)-α levels while improving insulin resistance." (PMID 40862455, 2025). "Studies in mice show that TNF administration induces insulin resistance, while its inhibition improves insulin sensitivity." (PMID 40453076, 2025).
Insulin resistance (continued). "Pro-inflammatory cytokines such as tumor necrosis factor-alpha (TNF-α) and interleukin-6 (IL-6) contribute to insulin resistance and vascular dysfunction, further complicating glucose metabolism." (PMID 40076938, 2025). "The TNF pathway emerged as a central link connecting chronic inflammation, insulin resistance, and tumor growth." (PMID 40547917, 2025). "When compared to TNF-α, IL-6 exhibits broader systemic effects, impacting both insulin resistance and ovarian physiology." (PMID 40385768, 2025). "TNF-α induces insulin resistance by disrupting post-receptor insulin signaling pathways, originates from adipose tissues, and acts as important cytokine in pro-inflammatory pathways." (PMID 40943380, 2025). "TNF‐α has a complex role in cancer and has been shown to contribute to insulin resistance and lipid metabolism, both in adults and children." (PMID 40901647, 2025). "Pro-inflammatory chemokines and cytokines, such as MCP-1, TNF-α, and IL-6, can induce insulin resistance through various mechanisms, including inflammation promotion and impairment of insulin sensitivity." (PMID 40286055, 2025). "These include elevated renal acid load, increased uremic toxins, promotion of insulin resistance, and elevated levels of pro-inflammatory cytokines such as TNF-α and IL-6." (PMID 40871720, 2025). "This inflammatory state disrupts insulin signaling, with cytokines such as tumor necrosis factor‐alpha (TNF‐α) and interleukin 6 (IL‐6) leading to insulin resistance and complications such as type 2 diabetes." (PMID 40968498, 2025). "The levels of blood glucose, lipids, insulin resistance (IR), Interleukin-6 (IL-6), interleukin-1β (IL-1β), tumor necrosis factor-α (TNF-α) were detected, and the pancreatic tissue damage was evaluated by Hematoxylin and eosin (H&E) staining microscope." (PMID 41098781, 2025). "In humans, the onset of insulin resistance coincides temporally with the emergence of TNF, a factor that is believed to act in concert with other cytokines." (PMID 39838305, 2025). "Inflammatory cytokines such as TNF-α, IL-1β, and IL-6 activate multiple signaling pathways, leading to insulin resistance, impaired insulin secretion, and promotion of diabetes and its complications." (PMID 41306290, 2025). "Insulin resistance and hyperinsulinemia, driven by TNF, activate pathways like PI3K/AKT, promoting cancer cell proliferation." (PMID 40547917, 2025). "Resistin promotes the secretion of pro-inflammatory cytokines such as TNF-α and IL-12 and is involved in glucose metabolism, insulin resistance, endothelial dysfunction, and vascular smooth muscle proliferation." (PMID 40095687, 2025). "In fact, it has been reported that IL‐10 prevents diet‐induced insulin resistance both in liver and skeletal muscle, through a reduction in the production of tissue IL‐6 and TNF‐α." (PMID 40207597, 2025). "Elevated levels of inflammatory markers such as IL-6, IL-17, and TNF-α are commonly observed in PCOS patients and are closely associated with follicular developmental arrest, insulin resistance, and metabolic syndrome." (PMID 41267865, 2025). "Analysis biochemical indicators revealed significant post-treatment differences in LDL-C, TC, Hcy, IL-6, TNF-α, 25(OH)D, and insulin resistance (IR) (P < 0.05)." (PMID 40963681, 2025). "Cachectic COPD phenotypes are marked by systemic inflammation (elevated IL-6 and TNF-α) and progressive muscle wasting, closely correlating with metabolic dysfunction and insulin resistance." (PMID 40283443, 2025). "Under obese conditions, a shift toward pro-inflammatory M1 macrophage polarization occurs, accompanied by increased production of cytokines such as TNF-α and IL-6, both of which disrupt insulin signaling and contribute to insulin resistance." (PMID 40869401, 2025).
Insulin resistance (continued). "MIF also contributes to the insulin resistance effects mediated by TNF-α due to the reduced AKT phosphorylation and, as a result, reduced phosphorylation of IRS-1, all necessary for signal transduction via the insulin receptor." (PMID 41296415, 2025). "Chronic low-grade inflammation, driven by adipose tissue macrophage infiltration and pro-inflammatory cytokines such as tumor necrosis factor (TNF)-α and interleukin (IL)-6, exacerbates insulin resistance." (PMID 41348748, 2025). "The mechanism by which TNF‐alpha induces insulin resistance is not fully understood, but one proposed pathway involves the activation of the JNK pathway, leading to serine 307 phosphorylation of insulin receptor substrate‐1 (IRS‐1)." (PMID 40551726, 2025). "TLR activation produces proinflammatory cytokines (TNF-α, IL-6, and IL-1β) that are essential in developing insulin resistance." (PMID 40076851, 2025). "Cytokines such as TNF-α and IL-6, released during trauma, exacerbate insulin resistance, further aggravating hyperglycemia." (PMID 40343929, 2025). "In the plasma of women with GDM pregnancy and their offspring, there were alterations in insulin resistance-related factors, such as elevated leptin, tumor necrosis factor-α (TNF-α), asprosin, and resistin." (PMID 40453589, 2025). "This prolonged activation amplifies the production of pro-inflammatory cytokines like tumor necrosis factor-alpha (TNF-α) and various interleukins, contributing to insulin resistance and systemic metabolic impairment." (PMID 40863143, 2025). "TNF-α is a key cytokine released from adipocytes and is known to dysregulate leptin and inhibit glucose-stimulated insulin secretion leading to insulin resistance." (PMID 41463113, 2025). "The PI3K/Akt signaling pathway mainly mediated the improvement of white sweet potato anthocyanins against TNF-α-induced insulin resistance." (PMID 40218884, 2025). "TNF-α is a pro-inflammatory cytokine that plays a key role in insulin resistance and metabolic disorders." (PMID 41574186, 2025). "While IL-6 and TNF-α actively contribute to insulin resistance and ovarian dysfunction, CRP serves as an indicator of the overall inflammatory status." (PMID 40385768, 2025). "The UPR also activates inflammasome-producing IL-1β and promotes the production of inflammatory cytokines such as TNF-α, inducing mitochondrial biogenesis impairment and insulin resistance." (PMID 40696355, 2025). "Specifically, IL-1β directly damages pancreatic β-cells, IL-6 affects glucose metabolism, and TNF-α plays a central role in peripheral insulin resistance." (PMID 39960958, 2025). "Pro-inflammatory cytokines (e.g., IL-6, TNF-α) derived from adipose tissue not only exacerbate insulin resistance but also foster a tumor-promoting milieu in the endometrium, creating a biological continuum linking these conditions." (PMID 40718420, 2025). "The increase in IL-6 and TNF-α in synchrony promotes the increase in C-reactive proteins and the decrease in adiponectin, which will increase the insulin resistance characteristic of a diabetic patient." (PMID 40141192, 2025). "In AT, resident γδ T cells promote insulin resistance through secretion of IL-17 and TNF-α, as well as by inducing pro-inflammatory macrophage polarization." (PMID 41341586, 2025). "Neuroinflammation is triggered through the release of some cytokines like interleukin 6 (IL-6) and tumour necrosis factor-alpha (TNF-alpha), which are products of inflammation and a key feature of insulin resistance, and they lead to cognitive impairment." (PMID 41280310, 2025). "The KD and VLCKD also improve insulin resistance, which in turn inhibits the production of IL-1α, IL-1β, IL-6, tumor necrosis factor α (TNF-α), and leptin." (PMID 40261944, 2025). "TNF-α can also directly affect muscle protein degradation and can contribute to the development of insulin resistance by reducing insulin-regulated glucose transporter levels and impairing the insulin signaling pathway." (PMID 40869715, 2025).
Insulin resistance (continued). "These important mechanisms are disruption of the blood-brain barrier, microglial activation, cytokine-related neurotoxicity (e.g., IL-6, TNF-alpha), lysosomal maladaptation, and metabolic imbalance (e.g., insulin resistance, hyperglycemia)." (PMID 40842786, 2025). "Visceral obesity and insulin resistance contribute to a pro-inflammatory state in which hypertrophied adipocytes and infiltrating immune cells secrete cytokines such as TNF-α, IL-6, and MCP-1." (PMID 40710574, 2025). "Typically, men possess a higher proportion of visceral fat and secrete more pro-inflammatory factors such as IL-6 and TNF-α, which promote insulin resistance and atherosclerosis." (PMID 40395813, 2025). "TNFα induces insulin resistance by directly inhibiting the insulin signaling pathway, modulating mitochondrial oxidative phosphorylation (OxPhos), and inducing oxidative stress signaling pathways." (PMID 39269560, 2025). "TNF, and interleukin-6 (IL-6) have been shown to disrupt insulin signaling, reducing glucose uptake and contributing to insulin resistance." (PMID 40453076, 2025). "Tumor necrosis factor α (TNFα), a potent inflammatory cytokine, promotes insulin resistance through the downregulation of key genes required for normal insulin function." (PMID 41012578, 2025). "Persistent immune activation in RA leads to excessive production of pro-inflammatory cytokines such as TNF-α, IL-6, and IL-1β, which contribute to hepatic insulin resistance and lipid accumulation." (PMID 40797381, 2025). "Tumor necrosis factor (TNF) is a major pro-inflammatory cytokine which plays a major role in inflammation, cancer, and insulin resistance." (PMID 40943574, 2025). "IMAT was measured via calf muscle MRI, and body composition (BMI, fat mass index), metabolic markers (hs‐CRP, TNF‐α, IL‐6, insulin resistance), and circulating cell‐free mitochondrial DNA (ccf‐mtDNA) were assessed." (PMID 40635410, 2025). "For example, insulin resistance can lead to increased infiltration of inflammatory cells in adipose tissue, which release pro-inflammatory cytokines such as tumor necrosis factor-alpha and interleukin-6, further promoting inflammation." (PMID 40983922, 2025). "TNF-α serves as a pivotal mediator within the inflammaging network, facilitating immune cell recruitment, endothelial dysfunction, and insulin resistance." (PMID 40507795, 2025). "TNF-α is a pro-inflammatory cytokine that impairs insulin signaling and intensifies insulin resistance." (PMID 40182806, 2025). "Increased concentrations of pro-inflammatory cytokines, including tumor necrosis factor-alpha (TNF-α), interleukin-6 (IL-6), and C-reactive protein (CRP), are implicated in the development of insulin resistance and the deterioration of pulmonary function." (PMID 40142617, 2025). "NF-κB is a key transcription factor involved in the production of pro-inflammatory cytokines such as TNF-α, IL-6, and IL-1β, which are elevated in conditions like obesity and insulin resistance." (PMID 40926269, 2025). "Elevated levels of inflammatory cytokines such as tumor necrosis factor α, interleukin 6, and C-reactive protein, commonly associated with FRAILTY and insulin resistance, have been implicated in DR pathogenesis." (PMID 40778361, 2025). "TNFα-induced NLRP3 activation in adipocytes causes mitochondrial dysfunction and exacerbates insulin resistance, while also impairing white adipocyte browning and thermogenic capacity." (PMID 40630101, 2025). "Inflammation in adipose tissue is mediated by the secretion of pro-inflammatory cytokines such as tumor necrosis factor-alpha (TNF-α) and interleukin-6 (IL-6), which can impair insulin signaling and promote insulin resistance." (PMID 40672421, 2025). "Conversely, adiponectin-KO mice exhibited severe insulin resistance and elevated serum TNFα following a two-week HFD challenge." (PMID 40868889, 2025).
Insulin resistance (continued). "This inflammatory state, characterized by elevated levels of cytokines such as interleukin-6 (IL-6) and tumor necrosis factor-α (TNF-α), which in turn exacerbate oxidative stress and insulin resistance, thereby promoting tumorigenesis." (PMID 41567806, 2025). "Some symptoms of a high‐fructose diet include insulin resistance, dyslipidemia, hyperinsulinemia, hypertension, increased tumor necrosis factor (TNF−), and decreased expression of adiponectin's protein and mRNA." (PMID 40772023, 2025). "Visceral fat also releases pro-inflammatory molecules like TNF-α and IL-6, which interfere with insulin signaling and worsen insulin resistance." (PMID 40612313, 2025). "WD-fed Icam1tmBay mice exhibited an increased insulin resistance and systemic inflammation, as evidenced by worsened glucose tolerance and increased circulating neutrophils and TNFα, suggesting a protective effect of ICAM-1 against metabolic dysregulation." (PMID 40670579, 2025). "This activation stimulates the NF-κB and MAPK pathways, promoting the release of proinflammatory cytokines (TNF-α, IL-6), insulin resistance, and chronic low-grade inflammation." (PMID 41373743, 2025). "An increased level of IL-17 activates an overabundant proinflammatory response by NF-kB signaling in adipose tissue, which results in the excessive production of IL-1β, IL-6, and TNF-α, contributing to insulin resistance." (PMID 40277935, 2025). "The most significant contributors to the development of insulin resistance are adiponectin, TNF-alpha, and IL-6, despite the fact that various other adipokines have been implicated in the pathogenesis of T2DM." (PMID 39791169, 2025). "Inflammatory factors from adipose tissue (TNF-α, IL-6) disrupt insulin signaling, exacerbating lipid synthesis and insulin resistance." (PMID 40129589, 2025). "Suppression of TNF-α and IL-6 levels restores a more normal inflammatory response, hence inhibiting the inflammatory condition that induces insulin resistance." (PMID 40218884, 2025). "Key inflammatory markers like IL-6 and TNF-α, central to PCOS pathophysiology and linked to insulin resistance, were significantly reduced by BL21, indicating its regulatory effect on inflammation and sex hormone balance." (PMID 39898662, 2025). "Insulin resistance leads to increased secretion of pro-inflammatory cytokines (e.g., IL-6, TNF-α), endothelial activation, and macrophage infiltration, all of which promote atherogenesis and plaque vulnerability." (PMID 40948866, 2025). "Among various inflammatory mediators, interleukin-6 (IL-6) and tumor necrosis factor-alpha (TNF-α) have been extensively studied for their contributions to both systemic insulin resistance and the metabolic alterations that occur during pregnancy." (PMID 40722699, 2025). "Adipose-derived inflammatory molecules, such as TNF-α, alter insulin signaling, promoting insulin resistance and impairing vascular health." (PMID 41373743, 2025). "VAT is metabolically active and by secreting free fatty acids and adipokines such as leptin, TNF-α, and IL-6 contributes to fostering systemic inflammation, endothelial dysfunction, and insulin resistance." (PMID 41141356, 2025). "Given the crucial role of hepatic inflammation in the development of insulin resistance, we examined the mRNA expression levels of two critical proinflammatory cytokines, IL-6 and TNF-α, using RT-qPCR." (PMID 39859525, 2025). "It is widely recognized that adipose tissue macrophages release tumor necrosis factor-α (TNF-α) and interleukin-6 (IL-6), which are involved in the development of insulin resistance." (PMID 40943118, 2025). "Elevated inflammatory markers like CRP and TNF-α in DKA and obese patients reflect the underlying inflammatory state, potentially contributing to insulin resistance." (PMID 40700071, 2025). "TFSE effectively reversed TNF-α-induced insulin resistance in 3T3-L1 adipocytes by enhancing insulin-stimulated glucose uptake, indicating anti-diabetic potential." (PMID 40807540, 2025).